SOCS3 (suppressor of cytokine signaling 3)
Diseases named in the same sentence as SOCS3 in open-access papers (continued):
Sharing a sentence is not in itself a finding about the gene and the disease.
retinitis (5 papers, 2018 to 2024). Inflammation of the retina. "Herein we review how SOCS1 and SOCS3 impact the virologic, immunologic, and/or pathologic outcomes of herpesvirus infection with particular emphasis on retinitis caused by HCMV or its mouse model experimental counterpart, murine cytomegalovirus (MCMV)." (PMID 31031749, 2019). "In addition to these in vitro models, we have observed in our laboratory that after intraocular (subretinal) MCMV inoculation of immunocompromised mice during experimental MCMV retinitis, SOCS1 and SOCS3 mRNA and protein are upregulated in retinitis-susceptible eyes." (PMID 31031749, 2019). "In comparison with the MCMV-infected eyes of animals immunosuppressed by LP-BM5 murine retrovirus infection, SOCS1 and SOCS3 were only moderately stimulated during less severe retinitis development within the MCMV-infected eyes of mice immunosuppressed by corticosteroid treatment." (PMID 34358000, 2021). "Furthermore, there is a decreased intraocular stimulation of SOCS1 and SOCS3 during experimental MCMV retinitis during corticosteroid-induced immune suppression that correlates with reduced severity of retinitis." (PMID 31031749, 2019). "If overexpression of SOCS1 and/or SOCS3 reduces retinitis severity, SOCS1 and/or SOCS3 mimetic peptides or overexpression treatment strategies could be efficacious against this disease, as with experimental autoimmune uveitis (EAU)." (PMID 31031749, 2019). "It attenuates diabetic retinopathy by alleviating retinal inflammation through upregulation of SOCS3 expression, suppression of toll-like receptor 4 (TLR4) signaling, and reduction of MMP-9 production, and of inflammatory factors including TLR4/p38/NF-κB signaling pathways in BV2 cells." (PMID 29937497, 2018). "Importantly, SOCS1 and SOCS3 are highly stimulated following subretinal MCMV infection in the retinitis-susceptible eyes of MAIDS-10 mice, but not in the MCMV-infected retinitis-resistant eyes of MAIDS-4 mice." (PMID 31031749, 2019). "In addition, SOCS1 and SOCS3 are highly stimulated following MCMV infection in retinitis-susceptible MAIDS-10 eyes, but not MCMV infected retinitis-resistant MAIDS-4 eyes." (PMID 31031749, 2019). "In a mouse model of experimental MCMV retinitis in the late-stage MAIDS, SOCS1 and SOCS3 were abundantly produced by macrophages, granulocytes, microglia, and Müller cells, suggesting their contribution to the severity of retinitis." (PMID 39066272, 2024). "SOCS1 and SOCS3 were not stimulated, and the severity of retinitis was reduced in the mouse model of experimental MCMV retinitis during corticosteroid-induced immunosuppression." (PMID 39066272, 2024). "Initial studies revealed that SOCS1 and SOCS3 (but not SOCS5) mRNA and protein were remarkably stimulated within the MCMV-infected eyes of MAIDS-10 mice during retinitis development." (PMID 34358000, 2021).
acute kidney injury (4 papers, 2015 to 2025). Sudden and sustained deterioration of the kidney function characterized by decreased glomerular filtration rate, increased serum creatinine or oliguria. "Suppressor of cytokine signaling 3 (SOCS-3), a key intracellular negative regulator of several signaling pathways, has been found to be strongly expressed in renal proximal tubules after acute kidney injury." (PMID 26089922, 2015). "Similarly, α7nAChR reduced the inflammatory response by modulating NF-κB (p65) and IL-6/JAK2/STAT3/SOCS3 signals in acute kidney injury (AKI) model." (PMID 37429998, 2024).
acute lung injury (4 papers, 2017 to 2025). A condition of lung damage that is characterized by bilateral pulmonary infiltrates (pulmonary edema) rich in neutrophils, and in the absence of clinical heart failure. "Resveratrol also inhibited CD45+Siglec F− and CD45+CD206− M1 subtype macrophages via the SOCS3 signaling pathway in a murine model of LPS-induced acute lung injury (ALI)." (PMID 41306613, 2025). "SOCS3 (suppressor of cytokine signaling 3) is a negative regulator of JAK/STAT3 signaling pathway and participates in the regulation of lung inflammation in a mouse model with acute lung injury (ALI)." (PMID 29284516, 2017).
airway hyperresponsiveness (4 papers, 2008 to 2025). "The abolition of SOCS-3 expression in T cells ameliorated ovalbumin-induced airway hyperresponsiveness in vivo." (PMID 18414649, 2008).
allergic rhinitis (4 papers, 2019 to 2025). Inflammation of the nasal mucous membranes caused by an IgE-mediated response to external allergens. "Studies have shown elevated SOCS3 levels in the case of allergic rhinitis." (PMID 31251775, 2019). "This study aims to investigate the expression and interaction mechanisms of Suppressor of Cytokine Signaling 3 (SOCS3) and Eotaxin in the nasal mucosal tissues of patients with Allergic Rhinitis (AR)." (PMID 40568590, 2025). "SOCS3 is part of the SOCS family, which are important modulators of inflammation and cytokine signalling, and were expressed in nasal epithelium of patients with allergic rhinitis." (PMID 34784380, 2021).
cytomegalovirus retinitis (4 papers, 2017 to 2024). Infection of the retina by cytomegalovirus characterized by retinal necrosis, hemorrhage, vessel sheathing, and retinal edema. "Because macrophages contribute prominently to the inflammation observed during cytomegalovirus retinitis and macrophages produce SOCS1 and SOCS3 during MAIDS-related MCMV retinitis, monolayers of mouse macrophages were used in these studies." (PMID 34358000, 2021). "It remains unclear, however, whether virus-induced stimulation of SOCS1 and/or SOCS3 is protective or pathogenic in the eye during MAIDS-related MCMV retinitis, an uncertainty that continues to motivate further investigations of SOCS and cytomegalovirus retinitis pathogenesis." (PMID 34358000, 2021).
dengue (4 papers, 2017 to 2023). "In dengue virus infection, immune evasion was associated with increased expression of IL-10-mediated SOCS3, which subsequently inactivated JAK/STAT pathways." (PMID 37376550, 2023). "For example, dengue virus infection was reported to drive IL-10-mediated SOCS3 expression and the consequent inactivation of JAK/STAT pathways." (PMID 32120897, 2020). "Since the levels of TNF-α, IL-6, and SOCS3 in the blood are higher in dengue-infected patients with hemorrhagic fever or shock (severe dengue) than those in patients with fever only, it suggests that overt inflammatory responses are detrimental to DENV-infected hosts." (PMID 36930690, 2023).
dermatitis (4 papers, 2011 to 2022). An inflammatory process affecting the skin. "Several other transcriptional changes in SKO mice parallel other models of wound healing and dermatitis including elevated expression of tenascin C (Tnc), osteopontin (Spp1), thrombospondin-1 (Thbs1) and Socs3." (PMID 21573029, 2011).
enteritis (4 papers, 2022 to 2024). Inflammation of the small intestine. "In terms of irinotecan-induced chemotherapeutic enteritis, ozone inhibits TF expression by activating the AMPK/SOCS3 pathway, thereby alleviating chemotherapeutic enteritis caused by ischemic–hypoxic injury." (PMID 37765024, 2023). "Activation of AMPK/SOCS3 has been shown to improve chemotherapy-induced enteritis and radiation-induced enteritis." (PMID 39628480, 2024). "Ozone therapy can activate AMPK/SOCS3, relieving chemotherapeutic enteritis." (PMID 38842109, 2024).
fibrosis (4 papers, 2015 to 2025). the formation of excess fibrous connective tissue in an organ or tissue in a reparative or reactive process. "Furthermore, SOCS3 expression was shown to be elevated for up to 30 days in bleomycin induced fibrosis." (PMID 32070329, 2020).
gout (4 papers, 2016 to 2025). A condition characterized by painful swelling of the joints, which is caused by deposition of urate crystals. "Our study identified SOCS3 as a central hub gene orchestrating gout‐associated inflammatory networks through integrated bioinformatics and machine learning approaches." (PMID 40613560, 2025). "In summary, our integrated bioinformatics analysis, machine learning approach, and clinical validation have identified SOCS3 as a pivotal diagnostic biomarker for gout, with its regulatory role intricately linked to PANoptosis ‐ related mechanisms." (PMID 40613560, 2025). "We carried out further studies to confirm the contribution of AMPK/SOCS3 in alleviating pain caused by gout." (PMID 38066599, 2023). "We identified the hub gene SOCS3 in gout and elucidated its mechanistic roles by integrated bioinformatics analysis, machine learning approach, and clinical validation, providing critical insights for advancing diagnostic biomarkers and therapeutic strategies in gout management." (PMID 40613560, 2025). "Notably, this differential association pattern suggests that SOCS3 may act as a pivotal regulatory hub in gout‐related inflammatory pathology by modulating the functional states of specific immune cell populations." (PMID 40613560, 2025). "Clinical validation via RT‐qPCR confirmed a strong consistency between SOCS3 expression levels in gout patients and computational predictions." (PMID 40613560, 2025). "Collectively, these findings underscore SOCS3 as a pivotal biomarker influencing PANoptosis‐driven inflammatory severity during acute gout episodes." (PMID 40613560, 2025). "Compared to the normal control group, SOCS3 was significantly upregulated in the gout group, and the area under the ROC curve (AUC) for both datasets reached 100%." (PMID 40613560, 2025). "Based on the screening analysis of the DSigDB drug database, Isoeugenol and Rofecoxib were identified as potential small‐molecule drugs targeting SOCS3 for gout treatment." (PMID 40613560, 2025). "Subsequent studies should employ in vitro and in vivo models to elucidate the mechanistic underpinnings of SOCS3 in gout pathogenesis." (PMID 40613560, 2025). "SOCS3 was significantly upregulated during gout flares (FC = 3.4) compared with normal SU, AH, and AH + MSU crystal deposition (FC = 1.1, 1.1 and 1.2, respectively, P < 0.0001 for each comparison)." (PMID 35731142, 2023). "This study reported on the expression of FFAR2 and SOCS3 genes in PBMCs during different pre-clinical, and clinical states in the gout hyperuricemia spectrum." (PMID 35731142, 2023). "SOCS3 was also upregulated during inter-critical gout (FC = 2.1) compared with normal SU (P = 0.02) and AH (P = 0.006) (FC = 1.1 and 1.2, respectively)." (PMID 35731142, 2023). "In this study, we proposed the molecular mechanism of ozone in the treatment of gout pain through AMPK/Gas6/MerTK/SOCS3/MMP9 for the first time." (PMID 38066599, 2023). "Our study showed that ozone inhibits TRLs signaling pathway by upregulating endogenous inflammatory brake SOCS3 to alleviate gout, which inhibit the activation of NLRP3 inflammasome at the upstream signaling pathway." (PMID 38066599, 2023). "Ozone reduces inflammation and alleviates gout pain by activating AMPK to up-regulate Gas6/MerTK/SOCS3 signaling pathway." (PMID 38066599, 2023). "We found that ozone promoted the release of GAS6 from macrophages and activated the MerTK receptor, further inducing SOCS3 expression to treat gout pain." (PMID 38066599, 2023). "Here we explored the molecular mechanism of ozone in treating gout pain by activating the TAM/SOCS3 signaling pathway." (PMID 38066599, 2023). "Some studies have shown that the expression of SOCS3 in synovium tissue increases in Gout patients in the regression phase." (PMID 38066599, 2023). "In conclusion, we have reported on the expression of FFAR2 and SOCS3 in the PBMCs of people with pre-clinical and symptomatic phases in the gout hyperuricemia spectrum." (PMID 35731142, 2023).
gout (continued). "Our data also support a role for rhIL-37 increased intracellular SOCS3 expression in the resolution of acute gout through the ability to negatively regulate proinflammatory cytokines and to switch on anti-inflammatory cytokine production." (PMID 27863506, 2016). "Notably, COX‐2 (PTGS2) and SOCS3 were co‐upregulated in gout patients and murine models, suggesting their potential as dual biomarkers for gout." (PMID 40613560, 2025). "Compared with health control, the expression of SOCS3 was upregulated in the gout group." (PMID 40613560, 2025). "Comprehensive analysis suggested that Isoeugenol and Rofecoxib may exert therapeutic effects on gout via SOCS3 modulation." (PMID 40613560, 2025). "Additionally, FFAR2 expression was significantly increased during gout flares compared with inter-critical gout, and SOCS3 gene expression was significantly increased early during gout flares." (PMID 35731142, 2023). "Indeed, our results showed upregulation of SOCS3 early during gout flares." (PMID 35731142, 2023). "IL‐6 activates STAT3 to promote neutrophil infiltration and joint inflammation, while SOCS3, a negative regulator of STAT3, is upregulated during gout flares, potentially mitigating inflammation by suppressing STAT3 signaling." (PMID 40613560, 2025). "FFAR2 expression was upregulated during gout flare compared with inter-critical gout and SOCS3 expression showed negative correlation with flare duration (r = –0.49, P < 0.05)." (PMID 35731142, 2023). "Recent studies have demonstrated that SOCS3 exhibits significantly elevated expression in monocytes and inflammatory tissues during the acute phase of gout, showing marked differences compared to individuals with normal serum uric acid (SUA) levels or those with asymptomatic hyperuricemia (AH)." (PMID 40613560, 2025). "SOCS3 is an inducible endogenous regulator of cytokine response through the inhibition of JAK/STAT signalling via a negative biofeedback loop, and this may explain increased gene expression early during a gout flare." (PMID 35731142, 2023). "Therefore, the objectives of this study were to examine the expression of FFAR2 and SOCS3 genes in people with normal serum urate (SU), asymptomatic hyperuricemia (AH), AH with asymptomatic MSU crystal deposition (AH + MSU), inter-critical gout and gout flare." (PMID 35731142, 2023). "There was no significant reduction in SOCS3 expression in inter-critical gout compared with gout flare, which may be due to the small sample size." (PMID 35731142, 2023).
Hyperinsulinemia (4 papers, 2012 to 2023). An increased concentration of insulin in the blood. "Although the MCK/SOCS3 mice showed normal glycemia on regular low fat diets, they did exhibit hyperinsulinemia." (PMID 23115649, 2012). "Therefore the increase of SOCS3 in the lungs of animals following pHA compared to Ctrl as shown in our study could contribute to the mild hyperinsulinemia and impaired glucose uptake after pHA at P21." (PMID 27087690, 2016). "The down-regulation of TLR4 combined with the lack of increased production of pro-inflammatory cytokines (i.e., IL-6 and TNF-α) and SOCS3 following insulin infusion in the current study suggested that hyperinsulinemia exerts an anti-inflammatory effect on the heart in non-obese individuals." (PMID 25101057, 2014).
hyperlipidemia (4 papers, 2012 to 2022). "That is, SOCS3, as a classic negative regulator of JAK2/STAT3, was up-regulated with the progression of inflammation aggravated by hyperlipidemia." (PMID 32169038, 2020).
hypertriglyceridemia (4 papers, 2016 to 2021). A laboratory test result indicating elevated triglyceride concentration in the blood. "SOCS3 is implicated in hypertriglyceridemia and functioning as a repressor of insulin signal transduction by inhibiting phosphorylation of IR as well as inducing degradation of IRS." (PMID 32158492, 2020). "SOCS3, which is a negative regulator of the JAK/STAT pathway is implicated in hypertriglyceridemia associated with insulin resistance and leptin resistance." (PMID 32158492, 2020).
osteoporosis (4 papers, 2019 to 2025). A condition of reduced bone mass, with decreased cortical thickness and a decrease in the number and size of the trabeculae of cancellous bone (but normal chemical composition), resulting in increased fracture incidence. "Recently, zoledronic acid, a drug used in osteoporosis and Paget’s disease, was reported to decrease SOCS3 expression in macrophages and improved the production of cytokines." (PMID 40104138, 2025). "Indeed, inhibiting SOCS3 in vitro, using shRNAs as well as the osteoporosis drug zoledronic acid, consistently reduced replication of WT and Delta SARS-CoV-2." (PMID 38238298, 2024).
periodontal disease (4 papers, 2013 to 2022). "We used a model of LPS-induced periodontal disease in rats to correlate SOCS3 expression with the inflammatory status." (PMID 24078776, 2013). "In this study we determined the kinetic of SOCS3 expression in a LPS model of experimental periodontal disease and correlated its expression pattern with dynamics of the inflammatory reaction, as assessed histologically/stereometrically and by the expression of pro- and anti-inflammatory cytokines." (PMID 24078776, 2013). "In this study we show that SOCS3 expression is increased both at the mRNA and protein levels in inflamed tissues, indicating a potential role of this gene in the pathogenesis and progression of periodontal disease." (PMID 24078776, 2013).
Salmonella Infections (4 papers, 2017 to 2025). Infections with bacteria of the genus SALMONELLA. "Confirming the initiation of an epithelial immune response by the intestinal barrier model, Salmonella infection induced the expression of both coding (SOCS3, CXCL2, CXCL3) and noncoding (NEAT1) immune-associated RNAs in IECs." (PMID 32071273, 2020).
spinal cord injury (4 papers, 2015 to 2025). Penetrating and non-penetrating injuries to the spinal cord resulting from traumatic external forces (e.g., WOUNDS, GUNSHOT; WHIPLASH INJURIES; etc.). "Although genetic manipulations of SOCS3 can enhance axonal regeneration after optic injury, the role of SOCS3 in dendritic outgrowth after spinal cord injury (SCI) is still unclear." (PMID 26384335, 2015). "Indeed conditional ablation of SOCS3, but not STAT3, produces contraction of lesion area and notable improvement in functional recovery after spinal cord contusion." (PMID 25750613, 2015).
Splenomegaly (4 papers, 2014 to 2023). Abnormal increased size of the spleen. "Hematopoietic-specific SOCS3 ablation was able to overcome these effects but resulted in the development of a lethal inflammatory disease, characterized by splenomegaly, pericarditis, hepatitis, and neutrophilia." (PMID 34604264, 2021). "Amongst other SOCS proteins, SOCS3 has also been found to have a role in basal granulopoiesis, with hematopoietic-specific SOCS3 deletion resulting in neutrophilia and splenomegaly, although only in more mature mice, with this attributed to enhanced G-CSF signaling." (PMID 37628937, 2023). "Higher SOCS3 levels have been shown to be associated with the lack of bulky lymphadenopathy and splenomegaly in CLL." (PMID 27107422, 2016). "In our study, SOCS-3 expression tended to be associated with the absence of adverse prognosticators, such as bulky lymphadenopathy or splenomegaly, creating the impression of behaving rather like a tumor suppressor." (PMID 24883303, 2014).